HLTF (helicase like transcription factor)
Diseases named in the same sentence as HLTF in open-access papers (continued):
Sharing a sentence is not in itself a finding about the gene and the disease.
cancer (28 papers, 2006 to 2024). A tumor composed of atypical neoplastic, often pleomorphic cells that invade other tissues. "To date, the expression of HLTF protein forms was reported in head and neck, cervix and thyroid cancers and associated with a poor prognosis." (PMID 29661164, 2018). "HeLa cells were used as a positive control because the cancer-associated truncated HLTF protein variants were discovered in these cells." (PMID 25005870, 2014). "This association makes HLTF a candidate as a cancer methylation biomarker." (PMID 34827720, 2021). "Interestingly, HLTF, the human homolog of Rad8, is often amplified and overexpressed in cancer, suggesting that HLTF causes GCRs and facilitates tumorigenesis." (PMID 34292936, 2021). "It has been suggested that the loss of expression of HLTF in several cancers (colon, gastric, esophageal, cervix, lung, hepatocellular, and bladder) may be caused by promoter methylation, as the downregulation of HLTF is correlated with hypermethylation of the promoter region." (PMID 34827720, 2021). "Human HLTF can alter its expression in various cancers through the hypermethylation in the promoter region." (PMID 36987072, 2023). "We developed a cell line-derived xenograft (CDX) model and show for the first time that HLTF-deletion in cancer cells and the TME results in metabolic reprogramming that mitigates oxidative stress in lymphatic intravascular metastatic niches." (PMID 37682902, 2023). "For example, HLTF is involved in the RAD6-RAD18-dependent DNA damage tolerance pathway, and the alternation of HLTF expression in cancer is associated with poor prognosis." (PMID 35053609, 2022). "HLTF expression is altered in cancer through two mechanisms: gene silencing by promoter hypermethylation or expression of truncated proteins that lack functional domains." (PMID 35154316, 2022). "(Fold change:0.058 and P<0.0001).HLTF gene expression changes in tissue samples demonstrated the reduction of expression in the cancer group compared with the normal group (Fold change:0.089 and P<0.0001)." (PMID 33936232, 2021). "Both HLTF and SHPRH were found to be down-regulated in several cancer types and HLTF is also up-regulated in various cancer types." (PMID 34407997, 2021). "Further studies should precisely investigate the functions of these HLTF protein forms and their role in cancer development." (PMID 29661164, 2018). "The hypermethylation of HLTF promoter was first identified in colon cancer and was reported in other types of cancers, including gastric cancers." (PMID 29661164, 2018). "We showed that HLTF expression increases significantly when comparing carcinomas to normal epithelia or dysplasias." (PMID 25005870, 2014). "In the context of cancer, HLTF silencing could thus both elevate replication stress resulting from G4s and increase the tolerance to that stress, driving mutagenesis." (PMID 39142279, 2024). "Also, the cancer group compared to the normal group in the HLTF gene of blood samples, showed the reduction of expression (Fold change: 0.051 and P<0.0001)." (PMID 33936232, 2021). "In cancer, two different alterations in HLTF expression were reported: (i) an epigenetic silencing by hypermethylation of its promoter and (ii) an alternative splicing of its mRNA, leading to the production of several shorter forms of the protein lacking DNA repair domains." (PMID 29661164, 2018). "Furthermore, HLTF and SHPRH are frequently inactivated in various cancers, and their loss increases the frequency of chromosome abnormalities during DNA damage indicating their importance in the maintenance of genomic stability and cancer suppression." (PMID 26350214, 2015). "Nuclear HLTF immunostaining could be used with FNA in an attempt to better distinguish benign thyroid nodules from malignant tumors." (PMID 25005870, 2014). "The physiological function of HLTF has not yet been fully understood, but evidence for its association with genesis and progression of cancer exists." (PMID 24708595, 2014).
cancer (continued). "Conceivably, targeting HLTF in chemotherapy-resistant cancers may lead to increase in cellular CP sensitivity." (PMID 24130896, 2013). "In conclusion, our data suggest that HLTF protein expression is linked to early transformation in a model of hormonal carcinogenesis and that HLTF protein detection might be of value as an early marker in some human cancers." (PMID 16762066, 2006). "In conclusion, both antisera developed against peptides of human HLTF could be used in the hamster cancer model." (PMID 16762066, 2006). "Notably then, HLTF silencing, which is often observed in cancers, may have a dual effect on cells, allowing the accumulation of mutagenic secondary DNA structures and permitting the replication fork to tolerate their presence." (PMID 39142279, 2024). "In addition, cancer patients who show resistance to HU treatment might have elevated levels of HLTF and SHPRH which tolerate the damage induced by the cancer drug." (PMID 34407997, 2021). "Interestingly, HLTF was found to be one of the genetic determinants conferring sensitivity or resistance to lysosomal autophagy inhibitors such as hydroxychloroquine (HCQ) in several cancer cell lines." (PMID 29807746, 2018). "Especially, 7 of ATPCRs showed a significant overexpression in multiple cancer types, including TTF2 (n = 6), RAD54L (n = 4), ACTL6A (n = 4), CHD7 (n = 3), HELLS (n = 3), HLTF (n = 3), and ACTR5 (n = 3)." (PMID 35789070, 2022). "HLTF and other members of the SWI/SNF family have been shown to be inactivated in several cancer types." (PMID 24198246, 2014). "Inactivation of the CSN-CRL4A/4BCDT2, RAD18, HLTF pathway reduces cell survival and promote apoptosis, suggesting that PRR may be considered as a potential target for cancer therapy." (PMID 23555860, 2013). "As a result, loss of RAD18 or UBC13 in BRCA1-deficient cancer cells does not abrogate reversed replication fork degradation, which is instead rescued upon knockdown of the fork reversal translocases SMARCAL1, ZRANB3 or HLTF." (PMID 38943334, 2024). "Using the network and pathway analysis, Helicase like transcription factor (HLTF) and SEPTIN 9 (SEPT9) genes were selected, since they are more specific than other genes as CRC biomarkers and less involved in the molecular pathways of other diseases and cancers." (PMID 33936232, 2021). "Lnc-HLTF-1, Lnc-HLTF-2 and Lnc-HLTF-3 are cancer-related although no function is currently assigned to them." (PMID 34010296, 2021).
adenocarcinoma (4 papers, 2012 to 2021). A common cancer characterized by the presence of malignant glandular cells. "The CDX model is predicated on the paucity of HLTF expression in the fibroblasts of the TME as shown in a well-differentiated adenocarcinoma from a male patient that resulted in hemicolectomy." (PMID 34010296, 2021).
infection (4 papers, 2018 to 2024). The state of being infected such as from the introduction of a foreign agent such as serum, vaccine, antigenic substance or organism. "HLTF is degraded by virion-associated HIV-1 Vpr early after infection in HeLa cells, the CD4+ T-cell lines: Jurkat and MT4 and in hMDMs." (PMID 39205287, 2024). "Both UL145 transcript and newly synthesized protein were detected from 6 hr of infection, confirming that the protein is expressed sufficiently early to regulate HLTF." (PMID 30122656, 2018). "The RING E3 ligase helicase-like transcription factor (HLTF) was proteasomally degraded throughout early infection and potently inhibits viral immediate-early gene expression." (PMID 30122656, 2018). "HLTF was degraded in all three screens, and throughout early infection starting from 4 hr, which was confirmed by immunoblot." (PMID 30122656, 2018). "This approach revealed that helicase-like transcription factor (HLTF), a DNA helicase important in DNA repair, potently inhibits early viral gene expression but is rapidly degraded during infection." (PMID 30122656, 2018). "Helicase-like transcription factor (HLTF), a DNA helicase important for DNA repair, potently inhibits early viral gene expression but is rapidly degraded during infection." (PMID 34345215, 2021). "HIV-1 Vpr did not enhance infection of these cell types despite HLTF degradation." (PMID 39205287, 2024).
HLTF also shares sentences with these, for which no sentence is quoted: depression (2 papers); head and neck cancer (2); HIV-1 infection (2); acute myeloid leukemia (1); Aicardi Goutières syndrome (1); Anxiety (1); autism (1); breast carcinoma (1); cervical tumor (1); chronic kidney disease (1); Chronic Myeloid Leukemia (1); colorectal (1); epilepsy (1); follicular carcinomas (1); glioblastoma (1); Graves disease (1); Hashimoto thyroiditis (1); malignant rhabdoid tumours (1); neurodegenerative disease (1); pancreatic cancer (1); pancreatic ductal adenocarcinoma (1); periodontitis (1); polycythemia vera (1); renal tumors (1); retinoblastoma (1); schizophrenia (1); Sepsis (1); systemic lupus erythematosus (1); thyroid autoimmune diseases (1).